ENSG00000266076 (novel transcript)
Gene: Protein-coding gene on chromosome 17 (65,538,102 to 65,641,033, reverse strand). Ensembl gene ENSG00000266076.
Genetic constraint (gnomAD): Missense variants: 11 observed, 14.72 expected, observed/expected ratio (o/e) 0.75, 90% interval 0.47 to 1.24. Synonymous variants: 8 observed, 6.34 expected, observed/expected ratio (o/e) 1.26, 90% interval 0.72 to 1.88.